TMSB15C (thymosin beta 15C)
Description:
Plays an important role in the organization of the cytoskeleton. Binds to and sequesters actin monomers (G-actin) and therefore inhibits actin polymerization.
Tractability: No criterion of Open Targets' tractability assessment is met for any kind of drug.
Gene: Protein-coding gene on chromosome X (104,063,871 to 104,076,236, reverse strand). Ensembl gene ENSG00000269226.
Subcellular location: Cytoplasm, cytoskeleton
Gene Ontology:
Molecular function: actin monomer binding
Biological process: actin filament organization
Cellular component: cytoskeleton
Homologues: Orthologues: macaque TMSB15B (100% identical). Paralogues in human: TMSB15A (100% identical), TMSB15B (100% identical).